MGRN1 (mahogunin ring finger 1)
Description:
E3 ubiquitin-protein ligase. Mediates monoubiquitination at multiple sites of TSG101 in the presence of UBE2D1, but not of UBE2G1, nor UBE2H. Plays a role in the regulation of endosome-to-lysosome trafficking. Impairs MC1R- and MC4R-signaling by competing with GNAS-binding to MCRs and inhibiting agonist-induced cAMP production. Does not inhibit ADRB2-signaling. Does not promote MC1R ubiquitination. Acts also as a negative regulator of hedgehog signaling (By similarity).
Synonyms: KIAA0544; RNF156
Tractability: Antibody: its Gene Ontology location is reachable by antibodies, with high confidence; UniProt places it where antibodies can reach, with medium confidence. PROTAC: UniProt records ubiquitination sites on it; ubiquitination databases record sites on it; its protein half-life has been measured.
Gene: Protein-coding gene on chromosome 16 (4,616,493 to 4,690,977, forward strand). Ensembl gene ENSG00000102858.
Subcellular location: Early endosome; Cytoplasm, cytosol (Isoform 1); Nucleus; Cytoplasm, cytosol (Isoform 2); Cytoplasm, cytosol (Isoform 3); Cell membrane; Cytoplasm, cytosol (Isoform 4)
Subcellular location (Human Protein Atlas): Vesicles; Endoplasmic reticulum
Pathways (Reactome):
Immune System: Antigen processing: Ubiquitination & Proteasome degradation
Gene Ontology:
Molecular function: protein binding; protein sequestering activity; ubiquitin-protein transferase activity; ubiquitin protein ligase activity
Biological process: endosome to lysosome transport; negative regulation of adenylate cyclase-activating G protein-coupled receptor signaling pathway; negative regulation of G protein-coupled receptor signaling pathway; protein monoubiquitination; negative regulation of melanin biosynthetic process; negative regulation of smoothened signaling pathway; positive regulation of appetite; smoothened signaling pathway; protein ubiquitination
Cellular component: cytoplasm; cytosol; early endosome; extracellular exosome; membrane; nucleus; plasma membrane
Genetic constraint (gnomAD): Loss-of-function variants: 31 observed, 67.63 expected, observed/expected ratio (o/e) 0.46, 90% interval 0.34 to 0.62. The synonymous counts are far from expectation, so gnomAD's model fits this gene poorly and the ratio says little. Missense variants: 998 observed, 774.16 expected, observed/expected ratio (o/e) 1.29, 90% interval 1.22 to 1.36. Synonymous variants: 470 observed, 336.7 expected, observed/expected ratio (o/e) 1.4, 90% interval 1.29 to 1.51.
Homologues: Orthologues: chimpanzee MGRN1 (98% identical), guinea pig MGRN1 (89% identical), dog MGRN1 (89% identical), pig MGRN1 (88% identical), macaque MGRN1 (87% identical), mouse Mgrn1 (85% identical), rat Mgrn1 (79% identical), rabbit MGRN1 (79% identical), zebrafish mgrn1b (72% identical), tropical clawed frog mgrn1 (66% identical), zebrafish mgrn1a (65% identical), Drosophila melanogaster Mrgn1 (40% identical), and 1 more. Paralogues in human: RNF157 (55% identical).
Diseases named in the same sentence as MGRN1 in open-access papers:
MGRN1 is named in the same sentence as 27 diseases in open-access papers, as found by Europe PMC text mining. Sharing a sentence is not in itself a finding about the gene and the disease. The quoted sentences say what the papers report.
spongiform encephalopathy (6 papers, 2013 to 2023). "A null mutation in MGRN1 results in a specific neuropathological change, spongiform encephalopathy." (PMID 36012221, 2022). "MGRN1 was identified by positional cloning of mahoganoid (md), a coat color mutation with pleiotropic and complex effects including spongiform neurodegeneration with features of prion diseases and congenital heart defects." (PMID 35892921, 2022). "The possibility that the same pathogenic mechanism might cause spongiform change in Mgrn1 null mutant mice and prion diseases was suggested by the observation that cytosolically exposed forms of PrP can bind to and sequester MGRN1." (PMID 23383230, 2013). "This caused endo-lysosomal trafficking defects similar to those observed when Mgrn1 expression is knocked down, implicating disrupted MGRN1-dependent trafficking in the pathogenesis of prion disease." (PMID 23383230, 2013). "Moreover, TSG101-null-mutant mice developed the same severe spongiform encephalopathy as MGRN1-mutant mice." (PMID 36012221, 2022). "This morphological evidence supports the hypothesis that Atrn and MGRN1 are involved in the clearance of an unknown substrate whose accumulation leads to spongiform encephalopathy." (PMID 36012221, 2022). "It is perfectly justified to extrapolate that simultaneous modulation of the two very heavily utilized arms of lysosomal degradation by the ubiquitously expressed MGRN1 could govern neurodegeneration in some types of prion diseases." (PMID 26539917, 2015). "Since the Tg(Mgrn1I)C3Tmg transgene has been shown to rescue vacuolation associated with loss of Mgrn1, this suggests that loss of MGRN1-dependent cellular processes is not the underlying cause of spongiform encephalopathy caused by RML prions." (PMID 23383230, 2013). "Together, these data suggest that the presence of cytosolic prion protein is not sufficient to cause prion disease and is not functionally equivalent to loss of MGRN1." (PMID 23383230, 2013). "We tested whether functional sequestration of MGRN1 by cytosolic PrP contributes to transmissible prion disease by inoculating mice expressing reduced or elevated levels of Mgrn1 with Rocky Mountain Laboratory (RML) prions." (PMID 23383230, 2013). "Mice lacking the Mahogunin Ring Finger 1 (MGRN1) E3 ubiquitin ligase develop spongiform encephalopathy by 9 months of age but do not become ill." (PMID 23383230, 2013). "However, a recent study using mice lacking the Mahogunin Ring Finger 1 (MGRN1) E3 ubiquitin ligase concluded that disruption of MGRN1-dependent pathways does not play a significant role in the pathogenesis of prion diseases." (PMID 24086135, 2013). "Mice lacking the E3 ubiquitin ligase, mahogunin ring finger-1 (MGRN1) or the type I transmembrane protein, attractin (ATRN) develop age-dependent CNS vacuolation that is histologically similar to that associated with prion diseases, without the accumulation of protease-resistant PrPSc." (PMID 23383230, 2013).
melanoma (5 papers, 2020 to 2025). A malignant, usually aggressive tumor composed of atypical, neoplastic melanocytes. "Mahogunin Ring Finger 1 (MGRN1), a ubiquitin ligase expressed in melanocytes, interacts with the α melanocyte-stimulating hormone receptor, a well-known melanoma susceptibility gene." (PMID 35892921, 2022). "Transient MGRN1 depletion with siRNA or permanent knockdown in human melanoma cells by CRISPR/Cas9 caused an apparently MITF-independent switch to a more dendritic phenotype." (PMID 35892921, 2022). "In summary, transient depletion or permanent ablation of MGRN1 in human melanoma cells caused an apparently MITF-independent switch to a more dendritic phenotype, consistent with previous observations in mouse melanocytes." (PMID 35892921, 2022). "DAMP-associated fluorescence was lower in mouse melanocytes and melanoma cells when the expression of MGRN1 was abrogated by CRISPR-Cas9 or downregulated with specific siRNAs." (PMID 34921635, 2021). "Knockout of MGRN1 in mouse melanoma cells caused similar changes and impaired their lung colonization potential." (PMID 33019669, 2020). "We show that MGRN1 deficiency increases genomic instability and leads to a more differentiated phenotype with significant changes in the metastatic potential of mouse melanoma cells." (PMID 33019669, 2020). "Moreover, the knockdown of MGRN1 augmented the burden of DNA strand breaks in mouse melanoma cells, thus indicating that loss of MGRN1 led to genomic instability." (PMID 35892921, 2022). "Moreover, lower expression of MGRN1 is significantly associated with better survival of human melanoma patients." (PMID 33019669, 2020). "Therefore, it was of interest to analyze whether knockdown of MGRN1 in human melanoma cells caused a similar phenotypic switch." (PMID 35892921, 2022). "In silico analysis of melanoma datasets showed that MGRN1 expression is higher in human melanomas than in normal skin or nevi and that there is a significant correlation between lower MGRN1 expression in human melanoma with longer patient survival." (PMID 35892921, 2022). "Transient MGRN1 depletion or permanent knockdown in human melanoma cells led to a differentiated phenotype by an apparently MITF-independent mechanism." (PMID 35892921, 2022). "In mouse melanocytes and melanoma cells, a comparable phenotypic change was observed upon repression of MGRN1." (PMID 35892921, 2022). "Accordingly, the effects of MGRN1 knockdown on the phenotype of human and mouse melanoma cells were similar." (PMID 35892921, 2022). "Previous studies showed that MGRN1 modulates the phenotype of mouse melanocytes and melanoma cells, with effects on pigmentation, shape, and motility." (PMID 35892921, 2022). "To validate this in silico analysis we measured MGRN1 expression by dPCR in our cohort of melanoma biopsies." (PMID 35892921, 2022). "MGRN1-KO human melanoma cells also displayed an increased genomic instability, with a higher burden of DNA strand breaks." (PMID 35892921, 2022). "The data summarized thus far suggested that MGRN1 is overexpressed in melanoma compared with normal skin and has similar effects on the phenotype of human melanoma cells compared with mouse melanoma cells." (PMID 35892921, 2022). "We next analyzed the presence of DNA strand breaks, since we previously reported an increased burden of this type of lesion in MGRN1-deprived mouse melanocytes and melanoma cells." (PMID 35892921, 2022). "Here, we have extended these studies to human cells by analyzing several aspects of the phenotype of HBL melanoma cells after CRISPR/Cas9-mediated knockdown of the MGRN1 gene." (PMID 35892921, 2022). "To this end, we interrogated public databases for correlations between the expression of MGRN1 and relevant clinical parameters and we also used a collection of melanoma specimens previously obtained at the Biocruces Bizkaia Health Research Institute (BBHRI)." (PMID 35892921, 2022).
melanoma (continued). "In previous studies, we found that MGRN1-KO B16 mouse melanoma cells displayed a more differentiated phenotype with increased pigmentation, higher adhesion to collagen I, and low motility in 2D and 3D assays, compared to control cells." (PMID 35892921, 2022). "In fact, only in acute myeloid leukemia (LAML) was MGRN1 expression clearly higher than in melanoma." (PMID 35892921, 2022). "To this end, we compared the levels of the phosphorylated form of histone H2AX (γ-H2AX) in control and MGRN1-KO human melanoma cells using an immunocytochemical technique." (PMID 35892921, 2022). "We previously reported that Mgrn1-KO cells derived from either melan-a6 mouse melanocytes or B16 mouse melanoma cells are darker and show a higher melanin content than control, MGRN1-expressing cells." (PMID 34921635, 2021). "We found strong overexpression of the gene in melan-md1 cells and Mgrn1-KO clones derived from melan-a6 melanocytes or B16 melanoma cells." (PMID 34921635, 2021). "Accordingly, MGRN1 is an important determinant of the phenotype and aggressiveness of melanoma cells." (PMID 33019669, 2020). "For this purpose, we interrogated the TCGA database for correlations of high and low MGRN1 mRNA levels and clinical data, in a set of >450 melanoma patients." (PMID 33019669, 2020). "Accordingly, it was of interest to analyze a possible relationship of MGRN1 expression and survival of melanoma patients." (PMID 33019669, 2020). "Consistent with the phenotypic changes in MGRN1-depleted mouse melanocytes and melanoma cells, analysis of the melanoma cohort of the TCGA database showed that low MGRN1 expression is significantly associated with better human melanoma patient survival." (PMID 33019669, 2020). "MGRN1 knockout in B16-F10 melanoma cells also augmented pigmentation, increased cell adhesion to collagen, impaired 2D and 3D motility and caused genomic instability." (PMID 33019669, 2020). "We report here the first study on the biological consequences of lack of MGRN1 on motility, cell cycle progression and genomic stability, using a panel of Mgrn1-null melanocytes and melanoma cells." (PMID 33019669, 2020). "Given that activation of MC1R in human melanoma cells stimulates the clearance of DNA strand breaks generated by oxidative stress, a possible involvement of MGRN1 in this MC1R-dependent genoprotective action cannot be ruled out and deserves further analysis." (PMID 33019669, 2020). "The higher aggressivity of MGRN1-expressing melanoma cells was confirmed in an in vivo mouse melanoma model and is consistent with higher survival of human melanoma patients expressing low levels of MGRN1." (PMID 33019669, 2020). "Whatever the contribution of MGRN1 to melanomagenesis, a role of its expression level in melanoma progression is likely, according to our data." (PMID 33019669, 2020). "It was therefore interesting to test the possibility that the level of MGRN1 expression in human melanoma tumors might have an impact on the course of the disease." (PMID 35892921, 2022). "Accordingly, MGRN1 should be further analyzed as a potential melanoma biomarker." (PMID 35892921, 2022). "Moreover, we present preliminary evidence suggesting that MGRN1 expression is higher in human melanomas than in normal skin or nevi and pointing to an inverse correlation of MGRN1 expression in human melanoma with patient survival." (PMID 35892921, 2022). "We present here a study of the effects of MGRN1 knockdown in human melanoma cells." (PMID 35892921, 2022). "So far, the biological roles of MGRN1 have been most often investigated in cultured mouse cells or laboratory mice, and the data concerning the biological roles of MGRN1 in human melanocytes and melanoma cells are still scarce." (PMID 35892921, 2022). "To this end, we abolished MGRN1 expression in HBL human melanoma cells by CRISPR/Cas9." (PMID 35892921, 2022).
melanoma (continued). "In agreement with this hypothesis, we showed previously that MGRN1 is a key regulator of the phenotype of normal mouse melanocytes and melanoma cells, with marked effects on pigmentation, shape, and motility." (PMID 35892921, 2022). "In this setting, the determination of MGRN1 expression in clinical melanoma specimens might provide useful prognostic information." (PMID 35892921, 2022). "Therefore, ablation of MGRN1 expression in mouse melanoma cells decreased their metastatic potential." (PMID 35892921, 2022). "Work is underway to analyze possible changes in the motility and invasive potential of MGRN1-depleted human melanoma cells, and to further probe the clinical application of the determination of MGRN1 expression levels in melanoma by the analysis of larger cohorts of patients." (PMID 35892921, 2022). "We found that MGRN1 is overexpressed in human melanomas compared with normal skin." (PMID 35892921, 2022). "Indeed, data compiled in the GEPIA and TCGA databases showed that MGRN1 expression in surgical melanoma specimens was significantly increased compared to normal skin." (PMID 35892921, 2022). "Concerning human melanoma, analysis of data in the TCGA database is consistent with our in vivo data in the B16 mouse model, as highlighted by the inverse relationship between MGRN1 expression and patient survival." (PMID 33019669, 2020). "Indeed, Mgrn1-KO B16 melanoma cells were more differentiated as shown by higher melanin contents, and presented higher levels of DNA damage as shown by comet assays, γH2AX staining and altered ploidy." (PMID 33019669, 2020). "Conceivably, an augmented formation of DNA breaks resulting from enhanced ROS production might thus contribute to the higher steady-state level of these lesions in Mgrn1-null melanocytes and melanoma cells." (PMID 33019669, 2020). "These in vivo experiments showed that, at least in the B16 mouse melanoma model, MGRN1 expression may regulate the malignant phenotype, with effects on proliferation, adhesion, motility, lung colonization potential and maybe also on the rate of tumor growth." (PMID 33019669, 2020). "In any case our data strongly suggest that MGRN1 might be an important determinant of melanoma aggressiveness and warrant further studies to clarify its role in human melanoma." (PMID 33019669, 2020). "However, data concerning the roles of MGRN1 in human melanoma cells remain scarce." (PMID 35892921, 2022). "Interestingly, these data also suggested that the expression of MGRN1 might be higher in melanoma compared with healthy skin, again pointing to a role for MGRN1 in the malignant phenotype of melanoma cells." (PMID 35892921, 2022). "In addition, both in silico analysis and direct comparison of MGRN1 mRNA levels in nevi and melanoma samples from the BBHRI cohort suggested that MGRN1 gene expression might be higher in melanomas compared with nevi." (PMID 35892921, 2022). "Our previous finding that MGRN1-null mouse melanoma cells are less aggressive than control cells expressing normal levels of MGRN1 suggested that MGRN1 might be a useful biomarker in melanoma." (PMID 35892921, 2022). "Therefore, MGRN1 might have an important role in modulating the behavior of human melanomas and may even be a determinant of melanoma prognosis." (PMID 35892921, 2022). "Using pH-sensitive fluorescent probes, we found that downregulation of MGRN1 expression in melanocytes and melanoma cells increased the pH of acidic organelles, including melanosomes, strongly suggesting a previously unknown role of MGRN1 in the regulation of melanosomal pH." (PMID 34921635, 2021). "Using a variety of pH-sensitive fluorescent probes, we found that downregulation of MGRN1 expression significantly increased the pH of acidic organelles, thus accounting for the high specific activity of TYR in the melanosomes of MGRN1-deficient melanocytes and melanoma cells." (PMID 34921635, 2021).